CAMK1D (calcium/calmodulin dependent protein kinase ID)
Description:
Calcium/calmodulin-dependent protein kinase that operates in the calcium-triggered CaMKK-CaMK1 signaling cascade and, upon calcium influx, activates CREB-dependent gene transcription, regulates calcium-mediated granulocyte function and respiratory burst and promotes basal dendritic growth of hippocampal neurons. In neutrophil cells, required for cytokine-induced proliferative responses and activation of the respiratory burst. Activates the transcription factor CREB1 in hippocampal neuron nuclei. May play a role in apoptosis of erythroleukemia cells. In vitro, phosphorylates transcription factor CREM isoform Beta.
Synonyms: CaMKID; CKLiK; CaM-K1
Tractability: Small molecule: a structure with a bound ligand is known; a high-quality ligand is known; it has a high-quality binding pocket; it belongs to a druggable protein family. PROTAC: UniProt records ubiquitination sites on it; ubiquitination databases record sites on it; its protein half-life has been measured; a small molecule that binds it is known.
Target class: Protein Kinase; CAMK protein kinase group; Enzyme; CAMK protein kinase CAMK1 family; Kinase
Chemical probes: CS640 (high quality)
Gene: Protein-coding gene on chromosome 10 (12,349,547 to 12,835,545, forward strand). Ensembl gene ENSG00000183049.
Subcellular location: Cytoplasm; Nucleus
Subcellular location (Human Protein Atlas): Cytosol; Nucleoplasm; Basal body
Gene Ontology:
Molecular function: calcium/calmodulin-dependent protein kinase activity; protein binding; calmodulin binding; ATP binding; protein kinase activity; protein serine kinase activity
Biological process: positive regulation of phagocytosis; positive regulation of respiratory burst; regulation of dendrite development; regulation of granulocyte chemotaxis; positive regulation of neuron projection development; positive regulation of neutrophil chemotaxis; regulation of neuron projection development; signal transduction
Cellular component: cytoplasm; nucleus
Genetic constraint (gnomAD): Loss-of-function variants: 7 observed, 35.98 expected, observed/expected ratio (o/e) 0.19, 90% interval 0.11 to 0.37. The upper end of that interval is the gene's LOEUF score, 0.37, which puts it in group 1 of 6, group 1 being the genes least tolerant of losing a copy. Missense variants: 260 observed, 443.67 expected, observed/expected ratio (o/e) 0.59, 90% interval 0.53 to 0.65. Synonymous variants: 167 observed, 168.56 expected, observed/expected ratio (o/e) 0.99, 90% interval 0.87 to 1.13.
Homologues: Orthologues: chimpanzee CAMK1D (100% identical), macaque CAMK1D (100% identical), dog CAMK1D (98% identical), mouse Camk1d (98% identical), rat Camk1d (98% identical), guinea pig CAMK1D (93% identical), pig CAMK1D (90% identical), tropical clawed frog cdc123 (83% identical), rabbit CAMK1D (82% identical), zebrafish camk1da (81% identical), zebrafish camk1db (78% identical), Drosophila melanogaster CaMKI (58% identical). Paralogues in human: CAMK1 (71% identical), CAMK1G (65% identical), PNCK (57% identical), PSKH1 (39% identical), CAMKV (38% identical), CAMK2D (38% identical), CAMK2G (37% identical), DCLK1 (37% identical), CAMK2B (37% identical), CAMK2A (36% identical), PSKH2 (36% identical), DCLK2 (36% identical), and 10 more.
Diseases named in the same sentence as CAMK1D in open-access papers:
CAMK1D is named in the same sentence as 44 diseases in open-access papers, as found by Europe PMC text mining. Sharing a sentence is not in itself a finding about the gene and the disease. The quoted sentences say what the papers report.
type 2 diabetes (13 papers, 2008 to 2023). "Related studies have found that CAMK1D is associated with lung adenocarcinoma cells, type 2 diabetes mellitus, and essential hypertension." (PMID 37254650, 2023). "A single nucleotide polymorphism (SNP) genotyping of 11,530 cases pointed out that SNP rs10906115A of CDC123/CAMK1D was significantly associated with susceptibility to type 2 diabetes in the Japanese population." (PMID 35910194, 2022). "Of important relevance to this project, variants in Camk1d have replicated association with Type II diabetes and a recent study also found association of this gene to hypertension." (PMID 28792545, 2017). "In cis-eQTL analyses, the rs11257655 type 2 diabetes risk allele was more strongly and directly associated with increased expression of CAMK1D than CDC123 in both blood and lung." (PMID 25211022, 2014). "The CDC123/CAMK1D type 2 diabetes association signal on chromosome 10 spans an intergenic region between CDC123 and CAMK1D and also overlaps the CDC123 3′UTR." (PMID 25211022, 2014). "For both eQTLs, the rs11257655 type 2 diabetes risk allele is associated with increased CAMK1D transcript level, consistent with the direction of transcriptional activity we observed for this allele in islet and liver cells." (PMID 25211022, 2014). "On BTA-13, CDC123 and CAMK1D genes have been reported to participate in various functions of pancreatic beta-cell and genetic variants at this locus have been associated to type 2 diabetes susceptibility in human." (PMID 24636660, 2014). "In conclusion, we extend follow up studies of GWAS-identified type 2 diabetes-associated variants to the CDC123/CAMK1D locus on chromosome 10." (PMID 25211022, 2014). "In this study, we expand the lexicon of disease-associated functional regulatory variation by examining the type 2 diabetes-association signal at the CDC123/CAMK1D locus." (PMID 25211022, 2014). "Taken together, these data confirm that rs11257655 exhibits allelic differences in transcriptional enhancer activity and suggest it functions within a cis-regulatory element at the CDC123/CAMK1D type 2 diabetes-associated locus." (PMID 25211022, 2014). "Dnajc15 has been suggested to be involved in pronephros development in Xenopus embryos, and Camk1d has been associated with type 2 diabetes." (PMID 21408189, 2011). "Among other genes identified in the CIT analysis were TCF19, which has been associated with type 1 diabetes through GWAS, and CAMK1D, which has been associated with type 2 diabetes This supports the role of DNA methylation as a direct mediator between genetic variation and metabolic phenotypes." (PMID 27322064, 2016). "Thus, our study provides strong evidence of a functional variant underlying the type 2 diabetes association signal at the CDC123/CAMK1D locus acting through altered regulation in type 2 diabetes-relevant cell types." (PMID 25211022, 2014). "The rs11257655-T allele associated with type 2 diabetes risk displayed increased enhancer activity relative to the C allele, suggesting that increased expression of one or more genes, possibly CAMK1D or CDC123, may be associated with type 2 diabetes." (PMID 25211022, 2014). "We identified fourteen type 2 diabetes-associated genes discovered by the first waves of GWAS for which there was little prior evidence of their potential role in diabetes (Adam30, Adamts9, Camk1d, Cdc123, Cdkal1, Cdkn2a, Cdkn2b, Ext2, Hhex, Ide, Jazf1, Lgr5, Thada and Tspan8)." (PMID 23442068, 2013). "Of note, CAMK1D is an established candidate gene for type II diabetes in human GWAS, with additional evidence implicating it in hypertension." (PMID 28792545, 2017). "A very recently published study investigated associations of the type 2 diabetes risk alleles in JAZF1, CDC123/CAMK1D, TSPAN8/LGR5, THADA, ADAMTS9, and NOTCH2 with obesity, insulin sensitivity, and insulin secretion in 4516 Danes." (PMID 18714373, 2008).
type 2 diabetes (continued). "In the type 2 diabetes CDC123/CAMK1D GWAS (genome-wide association studies) locus, rs11257655 affects transcriptional activity by altering the binding of the protein complexes of FOXA1 and FOXA2, a potential molecular mechanism in type 2 diabetes." (PMID 35910194, 2022). "To determine whether CDC123 or CAMK1D are expressed in type 2 diabetes-relevant tissues, we measured and confirmed expression of both transcripts in human islets and hepatocytes." (PMID 25211022, 2014). "Furthermore, a meta-analysis of three GWASs detected six novel variants (in JAZF1, CDC123/CAMK1D, TSPAN8/LGR5, THADA, ADAMTS9, and NOTCH2) that were associated with type 2 diabetes." (PMID 20161779, 2010). "However, it is not unexpected that our study was unable to find significant associations between SNPs in JAZF1, CDC123/CAMK1D, TSPAN8/LGR5 and ADAMTS9 and type 2 diabetes, since the meta-analysis required more than 9000 samples for an 80% power." (PMID 20161779, 2010). "The mechanism by which CAMK1D may act in type 2 diabetes biology is unclear." (PMID 25211022, 2014).
diabetes (9 papers, 2013 to 2025). "Polymorphisms in the calmodulin-dependent kinase subtype D (CaMK1D) gene region are linked to an increased incidence of diabetes." (PMID 40248148, 2025). "CaMK1D mediates intracellular signalling downstream of Ca2+ influx and thereby exhibits amplifications of Ca2+signals and polymorphisms that have been implicated in breast cancer and diabetes." (PMID 32535836, 2020). "A study using mice as a model showed that highly selective calmodulin-dependent kinase inhibitors, such as CaMK1 selective inhibitors, can restore insulin sensitivity, confirming CaMK1D as a target for diabetes treatment." (PMID 40248148, 2025). "Increased protein expression levels and altered regulation of glucose processing have indicated a role for CaMK1D in diabetes." (PMID 32535836, 2020). "The CAMK1D (OMIM 607957) gene on 10p13 and CACNA1A (OMIM 601011) on 19p13.13 are also associated with diabetes." (PMID 30212560, 2018). "As diabetes is a condition linked to increased cardiovascular risk, it was unsurprising that our work revealed gene interaction between KLFs, particularly KLF-14, and genes associated with diabetic risk factors, such as CAMK1D, HHEX, JAZF1, and TCF7L2." (PMID 38672763, 2024). "While we confirm expression of CAMK1D and CDC123 in islets and hepatocytes, future studies over-expressing the target gene(s) in these tissues would be necessary to establish the mechanisms by which increased expression leads to diabetes risk." (PMID 25211022, 2014).
breast carcinoma (6 papers, 2011 to 2022). "For example, CAMK1D (localized at chr.10p13) was highly expressed in basal-like breast cancer due to its gene amplification and exogeneous overexpression could induce EMT26." (PMID 35729213, 2022).
Obesity (6 papers, 2008 to 2025). Accumulation of substantial excess body fat. "CAMK1D has been suggested to play a role for liver gluconeogenesis, fat mass deposition, obesity and reduced insulin sensitivity." (PMID 39754479, 2025).
glioma (4 papers, 2021 to 2025). A benign or malignant brain and spinal cord tumor that arises from glial cells (astrocytes, oligodendrocytes, ependymal cells). "To understand the potent mechanisms underlying the role of CAMK1D in regulating glioma proliferation, invasion, and migration, we analyzed DEGs between high and low CAMK1D groups in TCGA." (PMID 35494053, 2022). "We found that downregulation of CAMK1D was associated with poor prognosis in glioma patients." (PMID 35494053, 2022). "In addition, CAMK1D expression in the database was associated with overall survival in patients with glioma." (PMID 35494053, 2022). "In a previous study, we demonstrated that CAMK1D exerts a significant influence on glioma cell invasion through the phosphatidylinositol-3-kinase/protein kinase B/mammalian target of rapamycin (PI3K/AKT/mTOR) signaling pathway." (PMID 41050075, 2025). "Prior investigations have elucidated CAMK1D’s role in promoting glioma cell proliferation, migration, and invasion through the activation of the PI3K/AKT/mTOR signaling pathway." (PMID 38720162, 2024). "In terms of mechanism, this study found that CAMK1D regulates the function of glioma cells by the PI3K/AKT/mTOR pathway." (PMID 35494053, 2022). "Kaplan–Meier survival analysis shows that CAMK1D can be used as a potential prognostic indicator to predict the overall survival of glioma patients." (PMID 35494053, 2022). "This study aimed to investigate the roles of CAMK1D in the proliferation, migration, and invasion of glioma." (PMID 35494053, 2022). "To investigate the signaling pathway involved in the regulatory mechanism of CAMK1D in glioma, we predicted and determined that the PI3K/AKT/mTOR pathway was critically involved in the inhibitory effect of CAMK1D in glioma." (PMID 35494053, 2022). "Our results show that the expression of CAMK1D in glioma tissues was decreased in aged and higher WHO grade patients." (PMID 35494053, 2022). "These in vivo findings showed that CAMK1D inhibited the proliferative ability of U251 glioma cells, which was consistent with our findings in in vitro experiments." (PMID 35494053, 2022). "Transwell and wound healing assays identified that knockdown of CAMK1D promoted the invasion and migration of glioma cells." (PMID 35494053, 2022). "First, the relative level of CAMK1D in glioma and its relation with overall survival of glioma were analyzed using bioinformatics." (PMID 35494053, 2022). "The result revealed that low CAMK1D expression was significantly related with the poor overall survival of glioma patients." (PMID 35494053, 2022). "We found that CAMK1D expression was significantly downregulated in glioma cell lines and glioma tissues from patients." (PMID 35494053, 2022). "The results revealed that glioma cell invasion and migration were weakened by CAMK1D overexpression." (PMID 35494053, 2022). "In conclusion, these findings suggest that CAMK1D serves as a prognostic predictor and a new target for developing therapeutics to treat glioma." (PMID 35494053, 2022). "We found that overexpression of CAMK1D can inhibit the proliferation, migration, and invasion of glioma cells, whereas knockdown of camk1d using siRNA produced opposite effects." (PMID 35494053, 2022). "Through online datasets, Western blot, and immunohistochemical analysis, glioma tissue has significantly lower CAMK1D expression levels than normal brain (NB) tissues, and CAMK1D expression was positively correlated with the WHO classification." (PMID 35494053, 2022). "In summary, we found that CAMK1D promotes glioma cell proliferation, migration, and invasive processes through activation of the PI3K/AKT/mTOR signaling pathway." (PMID 35494053, 2022). "The in vitro data suggest that CAMK1D represses glioma cell proliferation, invasion, and migration abilities." (PMID 35494053, 2022). "Based on bioinformatics analysis and screening, our study was the first to determine the role of CAMK1D in cell proliferation, migration, and invasion of glioma cells." (PMID 35494053, 2022).
glioma (continued). "In addition, colony formation assay, cell counting Kit-8, and xenograft experiment identified that knockdown of CAMK1D promotes the proliferation of glioma cells." (PMID 35494053, 2022). "The mRNA and protein levels of CAMK1D were notably upregulated in glioma cells transfected with CAMK1D plasmids and were downregulated in glioma cells transfected with siCAMK1D, compared to the pcNC (transfected an empty vector) and siNC (transfected a scramble siRNA)." (PMID 35494053, 2022). "The role of CAMK1D in glioma cell proliferation, invasion, and migration was also explored." (PMID 35494053, 2022). "Thus, we cannot rule out the possibility that other pathways are involved in the effect of CAMK1D in glioma, which deserves further investigation in our future studies." (PMID 35494053, 2022). "This implies that whether CAMK1D can be used as a prognostic marker for glioma patients needs to be studied in a larger collection of glioma specimens." (PMID 35494053, 2022). "Then, we determined the effect of CAMK1D overexpression on PI3K/AKT/mTOR pathway in glioma cells." (PMID 35494053, 2022). "Finally, we investigated the potential mechanisms involved in CAMK1D-induced regulation of glioma." (PMID 35494053, 2022). "Nevertheless, the clinical significance and function of CAMK1D in glioma remain unknown." (PMID 35494053, 2022). "Similarly, the expressions of CAMK1D in 4 glioma cell lines were significantly lower than the NHA." (PMID 35494053, 2022). "Thus, other functions of CAMK1D in glioma needs to be further studied." (PMID 35494053, 2022). "In a previous study, we established that CAMK1D, a member of the CAMK family, influences the malignant progression of glioma via the PI3K signaling pathway." (PMID 41050075, 2025). "Western blot analysis showed that overexpression of CAMK1D downregulated p-Akt, p-mTOR, and p-P70S6K, and decreased p-Akt/Akt, p-mTOR/mTOR, and p-P70S6K/P70S6K ratios in glioma cells." (PMID 35494053, 2022). "The PCR results revealed that suppressing the expression of CAMK2B in the U251 glioma cell line did not significantly alter the expression patterns of CAMK1D." (PMID 41050075, 2025). "The results indicated that the expression of CAMK1D was strikingly downregulated in glioma tissues from patients at all 4 WHO grades compared with normal brain tissues." (PMID 35494053, 2022). "In this study, we did not determine whether CERB or HH3 pathway was involved in CAMK1D overexpression-induced inhibition of glioma." (PMID 35494053, 2022). "In addition, we did not examine whether CAMK1D has other functions in glioma, such as reducing apoptosis, affecting EMT, and autophagy." (PMID 35494053, 2022).
lung adenocarcinoma (4 papers, 2017 to 2026). A carcinoma that arises from the lung and is characterized by the presence of malignant glandular epithelial cells. "Overexpression of CAMK1D in lung adenocarcinoma cells promotes cell proliferation but inhibits vascular endothelial cell formation." (PMID 35494053, 2022). "Recently, both miRNAs were found to promote neoangiogenesis in endothelial cells in mouse models of lung adenocarcinoma through targeting of CAMK1D, an inhibitory kinase that can impair angiogenesis when over-expressed." (PMID 29137392, 2017). "We show that the transfer of miR-143-3p and miR-145-5p within extracellular vesicles from lung adenocarcinoma cells to endothelial cells reduces the levels of CAMK1D and increases tube formation by endothelial cells." (PMID 29137392, 2017). "The transcriptomic data revealed that five genes (CAMK1D, BCAS3, DNAH1, PDE10A, and C18orf63) were differentially expressed between lung adenocarcinoma patients and healthy individuals." (PMID 41868793, 2026).
lung carcinoma (4 papers, 2017 to 2025). "Lung cancer patients with reduced expression of CAMK1D, an inhibitory kinase in the calcium/calmodulin-dependent protein kinase family, have a poorer prognosis." (PMID 40375334, 2025). "By contrast, stromal expression of miR-143/145 in lung cancer promotes neoangiogenesis by targeting CAMK1D, an inhibitory kinase." (PMID 30225000, 2018).
schizophrenia (4 papers, 2018 to 2025). A major psychotic disorder characterized by abnormalities in the perception or expression of reality. "The direct molecular mechanism through which rs12777434 acts on BMI and schizophrenia is currently unclear; however, variants within CAMK1D have been shown to affect its gene expression, leading to altered glucose processing through decreased gluconeogenesis and increased glycogen storage." (PMID 35342390, 2022). "Additionally, we identified fifty-five common and rare variants that exhibited gene-interaction effects including three variants in the CAMK1D gene and four variants in LHPP; both genes are linked to schizophrenia." (PMID 35342390, 2022). "The CAMK1D, GABRB3, and RBFOX1 genes have been suggested to contribute to schizophrenia physiopathology." (PMID 30034349, 2018).
Hypertension (3 papers, 2017 to 2023). The presence of chronic increased pressure in the systemic arterial system. "Subsequently, a congenic strain with the substitution of only 17q12.3 identified Camk1d and Plxdc2 as candidate genes for hypertension and dyslipidemia in the LH strain." (PMID 28792545, 2017).